IL21 (interleukin 21)
Diseases named in the same sentence as IL21 in open-access papers (continued):
Sharing a sentence is not in itself a finding about the gene and the disease.
posterior uveitis (1 paper, 2012). Inflammation of the choroid as well as the retina and vitreous body. "Taking together, we hypothesize that CFH-rs800292, IL-27-rs4788084, and rs4505848 within the KIAA1109/Testis nuclear RNA-binding protein (Tenr)/IL2/IL21 gene cluster might be involved in the pathogenesis of IU and posterior uveitis." (PMID 22876110, 2012).
primary sclerosing cholangitis (1 paper, 2022). "During follow-up, 3 patients (25%) with high IL-21 developed primary sclerosing cholangitis (PSC) variant syndrome." (PMID 35368991, 2022).
Pruritus (1 paper, 2023). Pruritus is an itch or a sensation that makes a person want to scratch. "Specifically, the percentage of Th17 cells in peripheral blood and the levels of IL‐17, IL‐21, and TGF‐β1 increased with the intensity of pruritus." (PMID 37506162, 2023). "Our findings revealed a significant positive correlation between the percentage of Th17 cells in peripheral blood, as well as the levels of serum IL‐17, IL‐21, and TGF‐β1, with the degree of pruritus, disease severity, and impaired quality of life in CSU patients." (PMID 37506162, 2023).
renal dysfunction (1 paper, 2020). "Linear regression analysis revealed a good correlation of serum IL-21 (ρ = −0.018, P = 0.016) and TNF-α (ρ = 0.006, P < 0.001) levels with serum creatinine (Cr), indicating that circulating cytokines could be a potential biomarker for monitoring renal dysfunction." (PMID 32991326, 2020).
Respiratory tract infection (1 paper, 2023). An infection of the upper or lower respiratory tract. "We also found that IL-21/IL-21R may exacerbate neutrophilic inflammation by modulating the TLR/MyD88 signaling pathway during C. muridarum respiratory tract infection." (PMID 37628738, 2023).
retinal diseases (1 paper, 2017). "In addition to being potent classifiers, IL-21, IL-10, and ACE may have distinct biological functions in these retinal diseases." (PMID 28128370, 2017).
severe combined immunodeficiency (1 paper, 2022). Severe combined immunodeficiency (SCID) comprises a group of rare monogenic primary immunodeficiency disorders characterized by a lack of functional peripheral T lymphocytes resulting in early-onset severe respiratory infections and failure to thrive. "In this study, we report a 4-month-old boy with T−B+NK− severe combined immunodeficiency (SCID) due to a novel mutation in exon 2 of IL2RG, the gene encoding the interleukin (IL) common gamma chain (γc) of the cytokine receptors for IL-2, IL-4, IL-7, IL-9, IL-15, and IL-21." (PMID 35498802, 2022).
Sezary syndrome (1 paper, 2022). Sezary syndrome (SS) is an aggressive form of cutaneous T-cell lymphoma characterized by a triad of erythroderma, lymphadenopathy and circulating atypical lymphocytes (Sezary cells). "IL-21 leads to more specific activation of STAT3 in Sezary Syndrome, which in turn directly upregulates IL-21 expression leading to an enhanced IL-21 autocrine signaling loop." (PMID 36505769, 2022).
sialoadenitis (1 paper, 2011). "Together these data suggest that IL-21 and IL-21Rpositive cells may play an important role in the sialoadenitis suffered by patients with primary SS." (PMID 22030011, 2011).
Skin rash (1 paper, 2014). A red eruption of the skin. "In phase 1 (n = 19), the maximum tolerated dose for IL-21 with the standard dose of sorafenib was determined to be 30 mcg/kg/day; grade 3 skin rash was the only dose-limiting toxicity." (PMID 24829759, 2014).
Skin ulcer (1 paper, 2016). A discontinuity of the skin exhibiting complete loss of the epidermis and often portions of the dermis and even subcutaneous fat. "Among the in vivo models, two mice in NC and IL-21 group with high amount of human T cell in peripheral blood died after tumor eradication and a few animals showed symptoms such as slightly arched back, hair ruffling, skin ulcer and diarrhea, which may be related to xenogeneic GVHD." (PMID 27409425, 2016).
vitamin D deficiency (1 paper, 2024). A nutritional condition produced by a deficiency of VITAMIN D in the diet, insufficient production of vitamin D in the skin, inadequate absorption of vitamin D from the diet, or abnormal conversion of vitamin D to its bioactive metabolites. "Vitamin D deficiency leads to diminished production of inflammatory cytokines, including IL-1, IL-6, IL-12, IL-21, and TNF-α, while enhancing the production of anti-inflammatory cytokines, such as IL-10." (PMID 39598148, 2024).
Wolfram syndrome (1 paper, 2021). Wolfram syndrome (WS) also known as DIDMOAD, is a neurodegenerative disorder characterized by type I diabetes mellitus (DM), diabetes insipidus (DI), sensorineural deafness (D), bilateral optical atrophy (OA) and neurological signs. "As compared with levels previously reported in heathy subjects, levels of IFN-γ, TNF-α, IL-1β, MIP-1β, MIP-3α, IL-21, and isoprostane were higher in study subjects with Wolfram syndrome." (PMID 34185708, 2021).
Zika virus infection (1 paper, 2023). "In Zika virus infection, Tfh cells enhanced the production of cytokines, such as IL-4 and IL-21, and also acted in a Th1-like manner, producing IFN-γ." (PMID 37514084, 2023).
tumor (458 papers, 2006 to 2026). "Namely, there has been an increase in T follicular helper cells and a decrease in pro-inflammatory IL-21 in patients’ serum, which indicates impaired function of these cells, possibly causing further immunosuppression and leading to tumor progression in NSCLC." (PMID 40427174, 2025). "We generated trifunctional antibody-cytokine fusion proteins composed of a scFv antibody directed against the fibroblast activation protein (FAP) as a tumor associated model antigen, IL-15 fused to an IL-15Rα fragment (RD), and either IL-7 or IL-21." (PMID 40370435, 2025). "By improving proliferation, tumor infiltration, cytokine secretion, and metabolic reprogramming, IL-21 can help address some of the major challenges associated with CAR-based therapies." (PMID 40176196, 2025). "Locally administered IL-21 in tumors has been shown to shift tumor-associated macrophages (TAMs) from the M2 phenotype towards the M1 phenotype, exerting anti-tumor effects." (PMID 40376002, 2025). "To delve deeper into the mechanism underlying the augmentation of MWA anti-tumor efficacy by IL-21, we employed flow cytometry and scRNA-seq to study the tumor-infiltrating CD8+T cells." (PMID 38833177, 2024). "Th17 cells play a crucial role in inflammation and tumor immunity through the secretion of Th17-associated cytokines such as IL-17A, IL-21, IL-23, and TNF46." (PMID 38172124, 2024). "IL-21 also enhanced the anti-tumor effect of combined PD-1/Tim-3 blockade in MHC I-deficient tumors by reinvigorating tumor-infiltrating NK cells." (PMID 37189417, 2023). "In a comparable preclinical study, Amgen Inc. developed a highly attenuated variant of IL-21 (R9E:R76A) and fused it to an anti-PD-1 antibody, and it provided protection against a humanized mouse tumor model that was resistant to anti-PD-1 monotherapy." (PMID 37483629, 2023). "Several recent studies demonstrate that IL21 can be produced by tumor-associated Tfh cells and IL21 promotes antitumor immunity through activating CD8+ T cells." (PMID 37546701, 2023). "scRNA-seq analysis of tumor-associated immune cells revealed that IL21-anti-HSA and anti-PD-1 synergistically promote the effector differentiation of T cells and DCs, and the type 1 polarization of monocytes and macrophages." (PMID 37546701, 2023). "Engineered Lister strain of VV with additional deletion of the VV 13.8-kDa N1L protein, a neurovirulence factor (named VVLΔTKΔN1L), and encoding IL-21 (VVLΔTKΔN1L-mIL-21) enhanced anti-tumour immune responses in murine models of colorectal cancer." (PMID 36140243, 2022). "CD4+ Th-CXCL13 recruits tumor-associated B cells and induces plasma cell differentiation and immunoglobulin production through interleukin-21 (IL-21) secretion and CD84 interactions in TLSs." (PMID 35663939, 2022). "Tc17 cells (characterised by IL-17A, IL-17F, IL-21, IL-22 production and low levels of granzyme B) have been associated with both anti-tumour (esophageal SCC patients) and pro-tumour activity (HNSCC patients)." (PMID 35406451, 2022). "To date, few studies have shown that IL-21-associated inflammation exists in human solid tumors, and the immune significance of IL-21 in the tumor microenvironment remains controversial." (PMID 34026621, 2021). "For instance, IL-2, IL-15, and IL-21 are reported to promote tumor suppression in melanoma, whereas IL-1, IL-4, and IL-6 are associated with tumor progression in breast, prostate, and lung cancer." (PMID 33800170, 2021). "IL-21 has also been used in studies of CAR-T for its ability to positively regulate tumor-associated immune cells." (PMID 34386015, 2021). "In conclusion, we report the infiltration of tumor-promoting Th17-like cells, expressing their related cytokines IL21 and IL26 and their association with particularly aggressive disease." (PMID 31948053, 2020).
tumor (continued). "Treatment with the dsNKG2D–IL-21 gene NPs caused increased secretion of serum IL-21 and activation of NK cells which retarded the growth of tumor and increased the life span of tumor-bearing mice." (PMID 33409265, 2020). "The expression of two genes associated with Th17 cells is intriguing since the Il21 mRNA level decreased in tumour tissue from treated mice, whereas Il17re was increased." (PMID 31595196, 2019). "High Blimp-1 expression, and concurrent high expression of both, IL-21R and its downstream target Blimp-1, were associated with poor survival of PDAC patients, implicating IL-21 in tumor progression." (PMID 31540511, 2019). "A few studies, in contrast, linked IL-21 with inflammatory colon carcinogenesis, tumor development or tumor progression." (PMID 31540511, 2019). "Taken together, IL-21 shifts T-cells towards an immunometabolic phenotype that has been associated with increased survivability and enhanced anti-tumor efficacy." (PMID 29568345, 2018). "We found that B/Mo/αGC vaccination restored the cytotoxic functions of Tim-3+PD-1+ NK cells in MHC class I-deficient tumours and that IL-21 was required for this process because the IL-21R blockade significantly abrogated the recovery of NK cell cytotoxicity." (PMID 28585539, 2017). "In experiments performed in tumors in IL-21-deficient mice, tumor cell proliferation (Ki-67) decreased, whereas cell apoptosis increased compared to wild-type mice." (PMID 25590298, 2015). "Increased IFN-γ expression in tumor-bearing IL-21-deficient mice caused increased tumor immunosurveillance, mediated by cytotoxic CD8+/CD103+ T cells targeting E-cadherin colonic tumor cells and therefore limited tumor growth." (PMID 25590298, 2015). "Other reports demonstrated that IL-21 enhances the activity of therapeutic mAbs, which target tumor-associated antigens." (PMID 25961061, 2015). "Only IL-21 was higher in tumor homogenates than in para-tumor homogenates (P < 0.001) and positively associated with recurrence-free survival (Gehan-Breslow-Wilcoxon test, P = 0.033)." (PMID 26517519, 2015). "Inflammatory Th17 cells and their associated cytokines (i.e., IL-17A, IL-17F, IL-21, IL-22, etc.)mediate tumor growth in two distinct ways – by driving angiogenesis and by suppressing antitumor immunity." (PMID 24987392, 2014). "Our study showed that levels of both INF-γ and IL-2 in mice treated with recombinant GM-CSF, IL-21 and Rae-1 gene expression vectors were highly expressed and negatively associated with the tumor volumes seen in tumor-bearing mice." (PMID 24350772, 2013). "Analysis of mechanisms underlying this effect revealed that IL-21 sustains CD4+ T cell infiltration in the tumor and peritumor areas and enhances the production of IL-6 and IL-17A as well as STAT3 activation." (PMID 23109839, 2012). "Similarly, IL-21 enhances the generation of less differentiated T-cell subsets, which are associated with improved persistence and anti-tumour activity." (PMID 40624498, 2025). "The outcomes of early clinical trials showed certain anti-tumor activities associated with IL-21." (PMID 38833177, 2024). "In addition, Fusobacterium nucleatum can induce the secretion of tumor-associated cytokines and inflammatory factors, such as IL-21/22/31 and CD40L, activating JAK/STAT and MAPK/ERK signaling pathways to promote tumorigenesis." (PMID 37460552, 2023). "Our findings provide evidence that IL-21-associated inflammation might be modulated within the tumor microenvironment and negatively influence the antitumor immune response." (PMID 34026621, 2021). "Next, we sought to determine whether IL-21 could directly induce the functional recovery of exhausted NK cells in MHC class I-deficient tumours." (PMID 28585539, 2017). "Because CD4+ T cells play a pivotal role in the growth of sporadic CRC, we next determined whether the diminished tumor incidence and severity in IL-21-deficient mice was associated with reduced infiltration and/or function of colonic CD4+ cells." (PMID 25839161, 2015).
tumor (continued). "IL-4, in collaboration with IL-21, is also essential for germinal center B cells maturation; we recently reported the importance of the interaction between germinal center B cells bearing Tet2 mutations and tumor cells in the pathogenesis of AITL using a murine model." (PMID 40164718, 2025). "These TFH cells secrete IL-21, which enhances granzyme B production in tumor-infiltrating CD8+ T cells, thereby potentiating cytotoxic antitumor activity." (PMID 41614936, 2026). "Our study, leveraging human cancer databases and tissue microarrays, identified a positive correlation between IL-21 and radiotherapy outcomes, particularly in tumor microenvironment (TME) activation." (PMID 41505202, 2026). "In mouse tumor models, IL-21 combined with radiation significantly enhanced the TME, boosting CD8+ T cell activation and function, reducing tumor burden, and extending survival." (PMID 41505202, 2026). "Mechanistically, GC B cells promoted IL-21 expression in Tfh cells, which in turn promoted CD8 effector differentiation, as IL-21 blockade, Il21 knockout, and ll21r knockout mice had enhanced tumor growth." (PMID 40356924, 2025). "Existing research suggests that targeting the B cell–Tfh cell–IL‐21 axis can enhance specific anti‐tumor immune responses." (PMID 41152153, 2025). "Our analysis of the relationship between tumor size and tumor secretions revealed that larger tumors were associated with higher levels of TNF-α, TNF-R2, IL-1α, IFN-α, MIP-1β, and IL-21." (PMID 39923035, 2025). "Tumor clearances were achieved in both IL-21 and IL-15 NK cells, with the highest proportions of cancer cell deaths induced by IL-21 NK cell cytotoxicity." (PMID 40027823, 2025). "By comparing the transcriptional profiles of CAR-15 and CAR-21 NK cells, we found that the anti-tumor effect can be enhanced by armoring CAR-NK cells with IL-21 to increase their metabolic fitness and effector function." (PMID 40176196, 2025). "In preclinical studies, IL-21 has demonstrated potent anti-tumor effects through mechanisms including the induction of interferon (IFN)-γ and the activation of NK and cytotoxic T cells." (PMID 39895691, 2025). "CAR-T cells cultured ex vivo and supplemented with IL-2 exhibited the least anti-tumor effect compared to the combination of IL-15 and IL-21." (PMID 40291594, 2025). "Glypican-3-CAR T cells have previously been developed as second-generation constructs, subsequently corroborated by the co-secretion of soluble cytokines like IL-15 and/or IL-21 for the improvement of anti-tumor function." (PMID 41465318, 2025). "For instance, dual-antigen–sensing CAR platforms can trigger IL-15 or IL-21 secretion only in tumor-restricted contexts, offering an added safety layer." (PMID 41584600, 2025). "To maximise the efficacy of Beads-FT-mA20T cells we co-treated tumour-bearing mice with oncolytic vaccinia virus armed with mouse interleukin-21 (OVV-mIL21) and TGF-β-blocking antibody (anti-TGFβ)." (PMID 40361460, 2025). "The combination of OVV equipped with IL-21 enhanced the anti-tumour activity of Beads-FT-mA20T cells and reduced metastasis." (PMID 40361460, 2025). "Clinical trials have indicated promise for IL-21 as an immunotherapeutic agent in the treatment of patients with metastatic melanoma, showcasing both a favorable safety profile and notable anti-tumor activity." (PMID 39895691, 2025). "The anti-tumor effect of TFH dependent TLS is mediated through interleukin 21 (IL-21) - IL-21 receptor signaling." (PMID 40027134, 2025). "In the TME, Tfh cells predominantly produce IL-21 cytokines, which facilitate humoral responses through the stimulation of B cell activation, class-switch recombination, and the secretion of anti-tumor IgG1 and IgG3." (PMID 40041860, 2025). "LDH-A inhibition combined with IL-21 in vitro promoted the formation of Tscm with increased anti-tumor activity in vivo after adoptive transfer." (PMID 41346587, 2025).